PMF1 (polyamine modulated factor 1)
Description:
Part of the MIS12 complex which is required for normal chromosome alignment and segregation and kinetochore formation during mitosis. May act as a cotranscription partner of NFE2L2 involved in regulation of polyamine-induced transcription of SSAT.
Tractability: PROTAC: ubiquitination databases record sites on it; its protein half-life has been measured.
Gene: Protein-coding gene on chromosome 1 (156,212,989 to 156,240,423, forward strand). Ensembl gene ENSG00000160783.
Subcellular location: Nucleus; Chromosome, centromere, kinetochore
Subcellular location (Human Protein Atlas): Nucleoplasm; Golgi apparatus; Vesicles
Pathways (Reactome):
Cell Cycle: Amplification of signal from unattached kinetochores via a MAD2 inhibitory signal; EML4 and NUDC in mitotic spindle formation; Mitotic Prometaphase; Resolution of Sister Chromatid Cohesion; Separation of Sister Chromatids
Signal Transduction: RHO GTPases Activate Formins
Gene Ontology:
Molecular function: leucine zipper domain binding; protein binding; transcription coactivator activity
Biological process: chromosome segregation; attachment of spindle microtubules to kinetochore; transcription by RNA polymerase II; positive regulation of DNA-templated transcription
Cellular component: kinetochore; MIS12/MIND type complex; nucleoplasm; outer kinetochore; cytosol; nucleus; spindle pole; transcription regulator complex
Genetic constraint (gnomAD): Loss-of-function variants: 19 observed, 22.65 expected, observed/expected ratio (o/e) 0.84, 90% interval 0.58 to 1.23. The upper end of that interval is the gene's LOEUF score, 1.23, which puts it in group 5 of 6, group 1 being the genes least tolerant of losing a copy. Missense variants: 242 observed, 244.31 expected, observed/expected ratio (o/e) 0.99, 90% interval 0.89 to 1.1. Synonymous variants: 94 observed, 99.75 expected, observed/expected ratio (o/e) 0.94, 90% interval 0.8 to 1.12.
Homologues: Orthologues: chimpanzee PMF1 (98% identical), rabbit PMF1 (83% identical), guinea pig PMF1 (78% identical), mouse Pmf1 (74% identical), rat Pmf1 (70% identical), tropical clawed frog bglap (46% identical), zebrafish si:dkey-6i22.5 (29% identical).
Diseases named in the same sentence as PMF1 in open-access papers:
PMF1 is named in the same sentence as 13 diseases in open-access papers, as found by Europe PMC text mining. Sharing a sentence is not in itself a finding about the gene and the disease. The quoted sentences say what the papers report.
COVID-19 (3 papers, 2023 to 2024). A disease caused by infection with severe acute respiratory syndrome coronavirus 2. "All above associations of alternative splicing, except for MUC1 and PMF1, were more pronounced as the severity of the COVID-19 outcome increased." (PMID 37794074, 2023). "MUC1 and PMF1 splicing is associated with COVID-19 susceptibility." (PMID 37794074, 2023). "In conclusion, we have used genetic determinants of alternative splicing and COVID-19 outcomes obtained from large-scale studies and found compelling evidence that splicing events in OAS1, ATP11A, DPP9, NPNT, MUC1, and PMF1 have causal effects on COVID-19 severity and susceptibility." (PMID 37794074, 2023).
bladder cancer (1 paper, 2023). "The methylation of PMF1 in bladder cancer patients has been associated with poor clinical outcomes." (PMID 38203489, 2023).
breast carcinoma (1 paper, 2022). "Six CDM genes (SRF, RAD51, PMF1, EXOSC3, EXOC1, and TSEN54) were found to be associated with the prognosis of breast cancer samples." (PMID 35096059, 2022). "The univariate and multivariate Cox regression analysis revealed that six CDM genes (SRF, RAD51, PMF1, EXOSC3, EXOC1 and TSEN54) were associated with the survival of patients with breast cancer." (PMID 35096059, 2022). "Also, by combining with Nrf-2, PMF1 could regulate the expression of SSAT, which affects the apoptotic cell death in breast cancer cells." (PMID 35096059, 2022).
ischemic stroke (1 paper, 2019). A stroke disorder caused by obstruction of blood flow to the brain, due to thrombotic (local blood clot formation) or embolic (due to a blood clot or other material traveling from another site) event. "We identified four novel eGFR-associated loci which have been previously associated with ischemic stroke in other studies, specifically USP38, ZFHX3, PMF1-BGLAP, and TTBK151–53." (PMID 31451708, 2019).
tumor (2 papers, 2015 to 2023). "Furthermore, in multivariable analysis, the authors found that among PMF-1 methylation status and clinical and pathological factors of sex, age, focality, tumor size, and concomitant CIS, only PMF-1 methylation was significantly associated with recurrence and progression." (PMID 37064102, 2023).
PMF1 also shares sentences with these, for which no sentence is quoted: cancer (1 paper); intracerebral hemorrhage (1); Leukoaraiosis (1); psoriasis (1); Spitz nevi (1); spitzoid melanoma (1); Stroke (1); transitional cell carcinoma of the bladder (1).